FSTL1 (follistatin like 1)
Diseases named in the same sentence as FSTL1 in open-access papers (continued):
Sharing a sentence is not in itself a finding about the gene and the disease.
pancreatic cancer (3 papers, 2016 to 2025). "The CCLE dataset revealed elevated expression of six module genes (GFPT2, MFAP5, CTSK, MMP2, FSTL1, and PRRX1) associated with poor overall survival in patients with pancreatic cancer." (PMID 40430018, 2025). "In conclusion, our study successfully identified a module of six key genes—GFPT2, MFAP5, CTSK, MMP2, FSTL1, and PRRX1—through Weighted Gene Co-expression Network Analysis (WGCNA) to assess cancer-associated fibroblast (CAF) infiltration in pancreatic cancer (PC)." (PMID 40430018, 2025). "In contrast to SPARC, FSTL1 was recently shown to inhibit pancreatic cancer growth." (PMID 29435136, 2018). "Consistent with this, FSTL-1 inhibited pancreatic cancer cell proliferation." (PMID 27886258, 2016). "In direct contrast to SPARC, however, FSTL-1 expression is reduced in pancreatic cancer." (PMID 27886258, 2016). "We also demonstrate for the first time that FSTL-1 suppresses pancreatic cancer cell growth." (PMID 27886258, 2016). "As yet, the role of FSTL-1 in pancreatic cancer and diabetes is unknown." (PMID 27886258, 2016). "Utilizing the CCLE database, it was confirmed that fibroblast cell lines exhibited elevated mRNA levels of the six module genes (GFPT2, MFAP5, CTSK, MMP2, FSTL1, and PRRX1) (accessed on 2 March 2025) compared to pancreatic cancer cell lines." (PMID 40430018, 2025). "We have further shown that FSTL-1 inhibits pancreatic cancer cell growth, suggesting that SPARC and FSTL-1 produced by stromal cells have antagonistic effects on cancer cell growth." (PMID 27886258, 2016).
silicosis (3 papers, 2017 to 2021). Silicosis is a respiratory disease caused by breathing in (inhaling) silica dust. "The findings reported in this study add new insights into our understanding of the regulation of silicosis and demonstrate the pro-fibrotic role of Fstl1 using a silica mouse model." (PMID 28341862, 2017). "The enhanced expression of FSTL1 in active fibrotic area of biopsy with silicosis was confirmed by IHC staining." (PMID 28341862, 2017). "In our experimental silicosis mouse model, we detected an increased circulating FSTL1 level in mouse serum after silica injury." (PMID 28341862, 2017). "We found elevated levels of follistatin like 1 (FSTL1) in serum from patients with silicosis and in lungs from silica-induced mouse model." (PMID 28341862, 2017). "Circulating FSTL1 levels in serum from patients with silicosis were markedly higher than that in healthy individuals." (PMID 28341862, 2017). "Circulating FSTL1 levels were quantified in serum from 37 patients with silicosis and 21 healthy controls." (PMID 28341862, 2017). "Consistently, we also measured elevated levels of FSTL1 protein in serum of patients with silicosis, when compared with those of healthy individuals." (PMID 28341862, 2017). "We provide data at clinical and animal levels, as well as proof of principle intervention to support a role of Fstl1 as a potential therapeutic target for silicosis." (PMID 28341862, 2017). "We offered the following lines of evidence to demonstrate the pro-fibrotic role of Fstl1 in silicosis." (PMID 28341862, 2017). "We also showed the elevated circulating FSTL1 levels in serum of patients with silicosis." (PMID 28341862, 2017). "Circulating level of FSTL1 was higher in serum of patients with silicosis." (PMID 28341862, 2017). "We further provide evidence that targeting FSTL1 with a neutralizing antibody may offer a potential therapeutic approach for patients with silicosis." (PMID 28341862, 2017). "However, whether FSTL1 may serve as a potential peripheral blood biomarker for silicosis still needs more intensively studies." (PMID 28341862, 2017).
Sjögren's syndrome (3 papers, 2011 to 2022). "According to these literature data, elevated FSTL1 serum levels were detected in patients affected by primary Sjögren’s syndrome (pSS)." (PMID 36143013, 2022). "In serum of RA patients, antibodies directed against FSTL1 appear more frequently (30%) than in other SADs, such as systemic sclerosis (17%), systemic lupus erythematosus (10%), and Sjögren’s syndrome (10%)." (PMID 29594389, 2018).
squamous cell carcinoma (3 papers, 2017 to 2024). A carcinoma arising from squamous epithelial cells. "We subsequently analyzed the relationship between FSTL1 and ZEB1 in other squamous carcinomas in the TCGA and GTEx data, and the data show that FSTL1 and ZEB1 expression are linearly correlated in these tumors." (PMID 38605354, 2024). "However, high variability in FSTL1 expression levels is observed in NSCL cell lines from both adeno- or squamous carcinomas." (PMID 29594389, 2018). "Although downregulation of FSTL1 in a squamous cell carcinoma (SCC12) cell line did not affect the proliferation rate in vitro, they were found to form larger tumours when injected in nude mice." (PMID 29594389, 2018). "In contrast, no prognostic significance was seen in FSTL1, BMP4, and Smad4 IHC expression in squamous cell carcinoma." (PMID 28852126, 2017).
Stroke (3 papers, 2012 to 2024). Sudden impairment of blood flow to a part of the brain due to occlusion or rupture of an artery to the brain. "qPCR results on Fstl1 levels only partly confirmed the transcriptomic data, being upregulated in all groups of pericytes in stroke animals, both in the ipsilateral and the contralateral hemisphere, but not in the groups of bulk cells." (PMID 37378751, 2024). "Of these Cort, which is also involved in sleep homeostasis remained downregulated on day14 post-stroke in both age groups, and Acvr1c, Htr2b and Fstl1 all involved in pain response, remained high at day14 in aged rats." (PMID 23251410, 2012).
acute kidney injury (2 papers, 2021 to 2022). Sudden and sustained deterioration of the kidney function characterized by decreased glomerular filtration rate, increased serum creatinine or oliguria. "We then determined whether FSTL1 was induced by acute kidney injury (AKI)." (PMID 35525270, 2022). "Fstl1 may play a role in cisplatin-induced acute kidney injury." (PMID 34502419, 2021).
aneurysm (2 papers, 2012 to 2022). Bulging or ballooning in an area of an artery secondary to arterial wall weakening. "In our other dataset (GSE54083), we were surprised to find that the expression of CDH11, SPARC, FN1, and FSTL1 in unruptured aneurysms was significantly increased, while WNT11, PCDH9, and GPC3 expression levels were relatively low." (PMID 34997174, 2022). "It was found that the expression levels of CDH11, SPARC, FN1, and FSTL1 genes in unruptured aneurysms were higher than those in healthy samples, while the expression levels of WNT11, PCDH9, and GPC3 in unruptured aneurysms were lower than those in healthy samples." (PMID 34997174, 2022).
Cachexia (2 papers, 2021 to 2024). Severe weight loss, wasting of muscle, loss of appetite, and general debility related to a chronic disease. "In cancer-induced cachexia, the levels of several myokines—including myostatin, IL-15, follistatin-related protein 1 (FSTL-1), fatty acid binding protein 3 (FABP3) and irisin—are elevated, suggesting that inhibition of myokines could be a therapeutical approach." (PMID 34899373, 2021). "Patients with cachexia had significantly higher levels of fatty acid-binding protein 3 (FABP3), follistatin-like 1 protein (FSTL−1), interleukin 6 (IL 6), and interleukin 8 (IL 8), while leptin concentrations in the peripheral blood were significantly lower." (PMID 39411315, 2024).
cardiomyopathy (2 papers, 2020 to 2025). A disease of the heart muscle or myocardium proper. "However, the effect of FSTL1 on DOX-induced cardiomyopathy has not been elucidated." (PMID 32831995, 2020).
cervical carcinoma (2 papers, 2023 to 2024). A carcinoma arising from either the exocervical squamous epithelium or the endocervical glandular epithelium. "Patients with a lower ratio of FSTL1 mRNA between the tumor and its matched adjacent tissues showed a correlation with the advanced cervical carcinoma FIGO stages." (PMID 36756161, 2023). "Our study has demonstrated the tumor suppressor effect of FSTL1, and these findings suggested a potential therapeutic target and biomarker for cervical carcinoma." (PMID 36756161, 2023). "We collected cervical carcinoma samples and matched adjacent tissues from patients with the locally-advanced disease and used cervical carcinoma cell lines HeLa and C33A to evaluate the effects of FSTL1 on CC cells." (PMID 36756161, 2023).
diabetic retinopathy (2 papers, 2021 to 2024). "FSTL1 may be involved in the pathogenesis of fibrosis in diabetic retinopathy caused by anti-VEGF (vascular endothelial growth factor) treatment." (PMID 34957094, 2021). "However, it has been reported that FSTL1 influences the progression of fibrosis in diabetic retinopathy, another type of diabetic microangiopathy, through the extracellular matrix (ECM) receptor pathway." (PMID 38390317, 2024).
emphysema (2 papers, 2021). "It was also found that laboratory mice showing low FSTL1 expression parameters were prone to spontaneous development of emphysema." (PMID 34440203, 2021). "Collectively, these data indicate that a decrease in the FSTL1 expression was a sufficient condition for the development of a histological, functional, and radiological picture of emphysema." (PMID 34440203, 2021). "Several FSTL1 SNPs were found corresponding to COPD and lung function, and FSTL1 deficiency might protect mice from cigarette smoke-induced emphysema." (PMID 33509151, 2021).
focal segmental glomerulosclerosis (2 papers, 2021 to 2024). A renal disorder characterized by sclerotic lesions in the glomeruli. "GSEA analysis revealed that the FSTL1 high-expression group was mostly concentrated in pathways like primary focal segmental glomerulosclerosis (FSGS), nephrotic syndrome, and IL-4 and IL-13 signaling and neutrophil degranulation." (PMID 38390317, 2024).
Hydroureter (2 papers, 2012 to 2015). The distention of the ureter with urine. "Disruption of Fstl1 causes multiple defects in developing urinary tract, including hydroureter arising from proximal segment as well as ureterovesical junction defects." (PMID 22485132, 2012). "Mouse embryos carrying disrupted Fstl1 gene displayed prominent hydroureter arising from proximal segment and ureterovesical junction defects." (PMID 22485132, 2012). "In this study, we report that Fstl1 knockout mice (Fstl1-/-) display a prominent hydroureter beginning at E16.0." (PMID 22485132, 2012). "In our study, the time point that subepithelial ureteral mesenchymal cells differentiated and the time point of hydroureter phenotype in Fstl1-/- to display are also concomitant." (PMID 22485132, 2012). "Although we observed that SHH signal is down-regulated in Fstl1-/- ureter, the hydroureter phenotype of Fstl1 ureter is more severe than Shh conditional mutant in ureteric epithelium." (PMID 22485132, 2012). "We found Fstl1 mutant embryos also displayed profound hydroureter and hydronephrosis at birth." (PMID 22485132, 2012).
infarction (2 papers, 2016 to 2026). A localised pathological necrosis of tissue resulting from obstruction of the blood supply usually by a thrombus, an embolus, or vascular torsion. "Together, these insights underscore the therapeutic promise of FSTL1 as a molecular target for enhancing cardiac repair and restoring myocardial integrity after infarction." (PMID 41602834, 2026). "In this review, we provide a comprehensive synthesis of current findings and propose an integrated framework in which FSTL1 orchestrates post-infarction healing through multiple signaling cascades, including BMP/SMAD, PI3K/AKT, MAPK, and TGF-β pathways." (PMID 41602834, 2026). "FSTL1 was detected in the cytoplasm of cardiomyocytes and appeared to be increased in the non-infarction area in the MI group." (PMID 27561749, 2016).
ischemic disease (2 papers, 2019 to 2022). Lack of blood supply to an area of the body, resulting in impairment of tissue oxygenation. "FSTL1 has been found to play an important role in promoting angiogenesis in tumor metastasis and in some ischemic diseases." (PMID 36091401, 2022). "Our data support the promise of Fstl1-overexpressing MSCs as a novel strategy to improve MSCs-based therapy for ischemic diseases." (PMID 30635025, 2019). "Therefore, FSTL1 may be critical in promoting angiogenesis in ischemic diseases by regulating blood glucose, VEGF, and cell matrix synthesis, which can all improve the symptoms and prognosis of ischemic diseases." (PMID 36091401, 2022).
joint diseases (2 papers, 2011 to 2023). "Elevated FSTL1 levels reflect not only joint diseases but also inflammation and tissue degradation in systemic autoimmune diseases." (PMID 21303509, 2011). "In contrast, available data suggest detrimental activity of FSTL1 in joint diseases, including OA." (PMID 37759715, 2023).
left ventricular hypertrophy (2 papers, 2016 to 2024). Enlargement of the LEFT VENTRICLE of the heart. "On the other hand, cardiac myocyte‐derived Fstl1 has been shown to be functionally significant in antagonizing myocyte hypertrophic growth in a model of left ventricular hypertrophy." (PMID 27234440, 2016). "Moreover, the potential role of FSTL1 in thecontext of left ventricular hypertrophy has been highlighted in studies,indicating that elevated serum FSTL1 levels in patients with chronic systolic HFcan serve as a reliable marker for left ventricular remodeling." (PMID 39077334, 2024).
liver disease (2 papers, 2024 to 2025). "For example, in liver diseases, FSTL1 exacerbates fibrosis by promoting inflammatory macrophage polarization and attenuating mesenchymal stem cell (MSC)-mediated immunosuppression." (PMID 40808692, 2025). "Some of the PBMC proteins have been previously connected to liver disease including FSTL1, TSP1, CCL5, and TPM2." (PMID 38335183, 2024).
lumbar disc herniation (2 papers, 2017 to 2019). "FSTL1 serum levels were significantly increased in lumbar disc herniation patients and had a positive correlation with Visual Analogue Scores." (PMID 28498809, 2017). "FSTL1 expression in the lumbar disc has not been reported and whether FSTL1 plays a pro-inflammatory role in the pathological processes of lumbar disc herniation is unknown." (PMID 28498809, 2017).
lung diseases (2 papers, 2017 to 2022). "Due to the high proportion of fibrotic patients developing PGD we compared FSTL1 serum concentrations between patients with fibrotic and non-fibrotic pulmonary disease." (PMID 36290379, 2022).
metastatic tumor (2 papers, 2015 to 2023). "The sMSC-derived FSTL1 might amplify such abnormal immunity by promoting the sMSC expansion in an autocrine manner as well as a paracrine manner by the metastatic tumor-derived FSTL1." (PMID 25883937, 2015).
osteoporosis (2 papers, 2020 to 2026). A condition of reduced bone mass, with decreased cortical thickness and a decrease in the number and size of the trabeculae of cancellous bone (but normal chemical composition), resulting in increased fracture incidence. "Targeting FSTL1 signaling may represent a promising therapeutic strategy for osteoporosis and other disorders of impaired bone remodeling." (PMID 41898202, 2026).
Parkinson disease (2 papers, 2021 to 2024). A progressive degenerative disorder of the central nervous system characterized by loss of dopamine producing neurons in the substantia nigra and the presence of Lewy bodies in the substantia nigra and locus coeruleus. "In the regulation of inflammation, HOXA11-AS mediated CaOx crystal-induced renal inflammation via the miR-124-3p/MCP-1 axis, while inhibition of HOXA11-AS repressed neuroinflammation and neuronal apoptosis in Parkinson’s disease model through through miR-124-3p-FSTL1-NF-κB axis and miR-98-5p/EphA4." (PMID 38902760, 2024).
renal cell carcinoma (2 papers, 2016 to 2023). "further found an SNP (rs1259293) in the genomic coding region of FSTL1, which is connected with a rising risk and poor postoperative prognosis of renal cell carcinoma." (PMID 36756161, 2023).
steatosis (2 papers, 2023 to 2024). Increased lipid within the cytoplasm of cells. "Follistatin-like protein 1 (FSTL1), a secretory glycoprotein, is a potential target for steatosis-associated liver fibrosis." (PMID 37770480, 2023). "To determine whether the serum FSTL1 level associated with liver pathology in humans, we analyzed specimens from 43 healthy participants, 43 patients with steatosis, 41 patients with early NASH and 53 with advanced NASH." (PMID 37770480, 2023). "FSTL1 expression is enhanced in the liver tissue and serum of patients with advanced fibrosis and steatosis." (PMID 39391493, 2024). "Although the FSTL1 level did not vary by age, BMI, plasma TG level, free fatty acid (FFA) levels, or cholesterol levels, we observed a significant positive correlation between FSTL1 expression and liver pathologies (steatosis, ballooning, fibrosis, and NAS)." (PMID 37770480, 2023). "Third, findings from in vitro studies showed that recombinant FSTL1 protein could rescue the steatosis cell phenotype." (PMID 37770480, 2023). "In conclusion, FSTL1 overexpression could counteract the effects of skeletal muscle IRF4 ablation in steatosis, fibrosis, and inflammation in NASH mice." (PMID 37770480, 2023). "Liver tissue H&E staining showed that the degree of steatosis and inflammation in F4MKO mice injected with AAV-FSTL1 were similar to that observed in Flox mice, which was further illustrated by the NAS scores of the liver tissue of Flox, F4MKO, and F4MKO + FSTL1 mice." (PMID 37770480, 2023). "FSTL1 could not restore cellular lipid accumulation and lipid metabolism gene expression in Dip2a or Cd14 knockdown AML12 steatosis cells co-cultured with GAS from F4MKO mice." (PMID 37770480, 2023).
abdominal aortic aneurysm (1 paper, 2025). Enlargement and ballooning of the vessel that supplies arterial blood to the abdomen, pelvis and legs. "Brown remodeling of white adipose tissue inhibited abdominal aortic aneurysm (AAA) progression via a vessel-protective adipokine Follistatin-like 1 (FSTL1), suggesting a novel therapeutic strategy for AAA intervention." (PMID 41068431, 2025).
acne (1 paper, 2024). An inflammatory process of the sebaceous glands which is characterized by comedones, nodules, papules and/or pustules on the skin. "Furthermore, cohort study results indicate a substantial impact on acne risk, with every one SD increase in the expression of FSTL1 and ANXA5 proteins associated with a 24% and 32% increase in the incidence of acne, respectively." (PMID 39493760, 2024). "Through MR analysis and examination of causality directions, 2 proteins (FSTL1 and ANXA5) were causally implicated in acne out of the 14 analyzed." (PMID 39493760, 2024). "The protein group differential analysis indicated that, For acne, the serum levels of FSTL1 and ANXA5 were significantly elevated in patients relative to the control group." (PMID 39493760, 2024). "Each one-standard deviation increase in the expression levels of FSTL1 and ANXA5 was associated with a 24% and 32% increase in acne incidence, respectively." (PMID 39493760, 2024). "This exploration successfully identified FSTL1 and ANXA5 as the potential protein targets for acne treatment." (PMID 39493760, 2024). "Our study reveals that the expression levels of FSTL1 and ANXA5 in the transcriptome at acne dermal lesions significantly exceed those in the normal control group." (PMID 39493760, 2024). "Further RNA-Seq differential analysis found that the expression of ANXA5 and FSTL1 in acne dermal lesions was significantly higher than in non-lesion sites." (PMID 39493760, 2024). "However, the expression of ANXA5 and FSTL1 in acne epidermal lesions was significantly lower than in non-lesion sites." (PMID 39493760, 2024). "To date, the relationship between FSTL1, ANXA5, and acne has not been extensively explored in the scientific literature." (PMID 39493760, 2024).